DDX39B (DExD-box helicase 39B)
Diseases named in the same sentence as DDX39B in open-access papers (continued):
Sharing a sentence is not in itself a finding about the gene and the disease.
malaria (1 paper, 2014). Malaria is a serious and sometimes fatal disease caused by a parasite that commonly infects a certain type of mosquito which feeds on humans. "The hypothesis that DDX39B may have an effect on the clinical presentation of malaria by its modulation of the expression of proinflammatory cytokines involved in the pathogenesis of the disease is appealing, but has not yet been tested." (PMID 25038626, 2014).
rectal adenocarcinoma (1 paper, 2022). "In addition, Sp1 expression was positively associated with DDX39B in colon and rectal adenocarcinoma patients from the TCGA database." (PMID 35973989, 2022). "We also found a positive correlation between Sp1 and DDX39B in colon and rectal adenocarcinoma patients from the TCGA database." (PMID 35973989, 2022).
vivax malaria (1 paper, 2014). "Given the major role of the host immune system in P. vivax infection, the aim of this study was to determine whether mutations in the DDX39B, TNF and IL6 genes were associated with the clinical outcomes of patients with vivax malaria." (PMID 25038626, 2014).
cancer (17 papers, 2014 to 2025). A tumor composed of atypical neoplastic, often pleomorphic cells that invade other tissues. "This application of PROteolysis Targeting Chimeras technology enables to inhibit the growth and metastasis of cancer cells by eliminating all functions of DDX39B protein." (PMID 40664668, 2025). "We also revealed that the genes with relatively high expression at 0 h were primarily related to cell growth and proliferation, particularly cancer cell proliferation, such as Tfap4, Rdm1, Ddx39b, Pgam1, and so on." (PMID 36834727, 2023). "A recent study has reported that the increased pre-ribosomal RNA levels of DDX39B augment global translation and cell proliferation of diverse cancer types." (PMID 35258800, 2022). "The mRNA expression levels of DDX39B in different cancer types were explored by TIMER, it is worth mentioning that its expression levels were higher in most cancer types than the normal tissues including the COAD and READ." (PMID 35046400, 2022). "DDX39A, a paralog of DDX39B, has been shown to have cancer-promoting activity in lung squamous-cell carcinoma, urinary bladder cancer, human malignant pleural mesothelioma, and hepatocellular carcinoma." (PMID 33436563, 2021). "DDX39B promotes cell proliferation by up-regulating pre-ribosomal RNA, and its levels are apparently improved in various cancer types." (PMID 32079071, 2020). "Similar to our study, mounting evidences regarded DDX39B as an important SF in triggering the progression and metastasis of various cancers." (PMID 31681747, 2019). "DDX39B protein levels were significantly augmented in cancer tissues compared with normal tissues." (PMID 40664668, 2025). "DDX39B was frequently upregulated in various types of cancers." (PMID 40664668, 2025). "Meanwhile, DDX39B has been found to be elevated in diverse cancers." (PMID 35046400, 2022). "However, the function of DDX39B in diseases such as cancer is largely unexplored and remains to be studied." (PMID 33436563, 2021). "In addition, DDX39B was frequently upregulated in many cancer types and promoted the proliferative capacity of cells." (PMID 32489474, 2020). "DDX39B is involved in the regulation of pre-mRNA splicing, nuclear export of mRNAs, and pre-ribosomal RNA translation, and may promote the genesis, development, and metastasis of multiple cancer types by regulating cell proliferation." (PMID 35003220, 2021). "Exploring the potential roles of SFPQ, DDX39B, and UBAP2 in other cancer types will also provide more information for developing precise treatment strategies." (PMID 39133261, 2024). "In recent years, the role of DDX39B in cancer has been more and more studied, but the mechanism of DDX39B in promoting the proliferation of CRC has not been elucidated." (PMID 35046400, 2022). "Although the functions of DDXs in cancers have recently been highly examined, the exact contribution of DDX39B to CRC has not yet been investigated." (PMID 33436563, 2021).
tumor (13 papers, 2019 to 2026). "Consistently, DDX39B deficiency not only inhibited tumor growth in subcutaneous tumor models in nude mice, but also suppressed spleen metastases in an orthotopic transplantation model of CRC and lung metastasis in a CRC model via tail-vein injection." (PMID 38023215, 2023). "We also found that 2-DG treatment significantly antagonized the increased tumor growth and metastasis formation in vivo caused by DDX39B upregulation." (PMID 35973989, 2022). "Elevated DDX39B protein expression was correlated with larger tumor size, poor histological grade, increased tumor invasion, higher incidence of metastasis to both regional lymph nodes and distant organs, and advanced AJCC stage." (PMID 35973989, 2022). "Overexpression of DDX39B enhances cell proliferation and global translation to promote tumor formulation." (PMID 33000861, 2020). "Here, we provided the first evidence that DDX39B protein expression was gradually upregulated from paracancerous tissue to primary tumor tissue to metastatic NSCLC tissue and that elevated DDX39B protein level was an independent indicator of poor overall survival in patients with NSCLC." (PMID 40664668, 2025). "Moreover, SUMOylated DExD-box helicase 39B (DDX39B)-mediated aberrant circNCOR1 export from the nucleus to the cytoplasm will decrease tumor suppression by circNCOR1." (PMID 36750826, 2023). "ST1926 treatment down-regulated a group of oncogenic proteins (SLC2A1, SLC25A6, CBX3, DEK, DDX39B) and up-regulated a group of presumably tumor-suppressing proteins (PEBP1, HspBP1); PADI2 and CMPK1, of unknown function in GBM, were also up-regulated." (PMID 37762371, 2023). "To further determine whether DDX39B was involved in the progression of CRC in vivo, we first examined the function of DDX39B on tumor growth by generating subcutaneous tumor models in nude mice." (PMID 35973989, 2022). "Our data suggested that DDX39B overexpression in CRC promoted CRC aggravation, which indicated that DDX39B may act as a tumor promoter in the development of CRC and thus needs to be thoroughly characterized." (PMID 33436563, 2021). "In conclusion, DDX39B acts as a tumor promoter in CRC by upregulating the expression of FUT3 and then promoting the fucosylation of TGFβR-I, which subsequently enhances activation of the TGFβ/SMAD2 signaling pathway to facilitate the invasion and metastasis of CRC." (PMID 33436563, 2021). "In our study, we found that abnormal expression of ASE of RHOT2 regulated by aberrant DDX39B could result in poor prognosis and tumor metastasis in patients with KIRC." (PMID 31681747, 2019). "Additionally, the association of SFPQ, DDX39B, and UBAP2 with angiogenesis-related genes underscores their critical roles in tumor angiogenesis and progression, offering valuable insights for personalized treatment strategies and prognostic prediction in HCC and PRAD." (PMID 39133261, 2024). "A stringent cross-comparison identified five proteins (PSAP, MARCKS, eEF1A1, DDX39B, and RACK1) as consistently and differentially regulated across tumor stages." (PMID 42064067, 2026). "Among them, DExD-Box Helicase 39B (DDX39B) was the only SF, who was correlated with prognosis, TNM staging system, clinical stage, and tumor purity." (PMID 31681747, 2019).
infection (7 papers, 2018 to 2025). The state of being infected such as from the introduction of a foreign agent such as serum, vaccine, antigenic substance or organism. "Co-immunoprecipitation experiments revealed the formation of DDX39B/THOC1/THOC4/CIP29/NP complexes during infection; as found earlier, RNase A treatment resulted in the loss of NP from the complex." (PMID 36084138, 2022). "Our study found that DDX39B was up-regulated in many of the sample conditions, which could be one of the methods the virus uses to avoid an inflammatory response after infection." (PMID 36204651, 2022). "On the other hand, MTX inhibits interactions of DDX39B with S protein and TMPRSS2, indicating that it may act against viral entry during the early stage of infection." (PMID 34709727, 2021).
DDX39B also shares sentences with these, for which no sentence is quoted: endometrial cancer (2 papers); bladder cancer (1); cervical cancer (1); colorectal adenoma (1); dental caries (1); female sterility (1); invasive carcinoma (1); lung carcinoma (1); metastatic tumor (1); multiple sclerosis (1); oropharyngeal cancer (1); pancreatic cancer (1); pancreatic ductal adenocarcinoma (1); renal cell cancer (1); soft tissue sarcoma (1).